TIGD5 (tigger transposable element derived 5)
Synonyms: FLJ14926
Tractability: PROTAC: ubiquitination databases record sites on it.
Gene: Protein-coding gene on chromosome 8 (143,597,831 to 143,603,224, forward strand). Ensembl gene ENSG00000179886.
Subcellular location: Nucleus
Gene Ontology:
Molecular function: DNA binding; nucleic acid binding
Biological process: animal organ development; central nervous system formation; segment specification
Cellular component: nucleus
Genetic constraint (gnomAD): Loss-of-function variants: 27 observed, 23.77 expected, observed/expected ratio (o/e) 1.14, 90% interval 0.84 to 1.57. The synonymous counts are far from expectation, so gnomAD's model fits this gene poorly and the ratio says little. Missense variants: 856 observed, 664.54 expected, observed/expected ratio (o/e) 1.29, 90% interval 1.22 to 1.36. Synonymous variants: 504 observed, 321.92 expected, observed/expected ratio (o/e) 1.57, 90% interval 1.46 to 1.68.
Homologues: Orthologues: chimpanzee TIGD5 (99% identical), macaque TIGD5 (98% identical), dog TIGD5 (90% identical), pig TIGD5 (86% identical), mouse Tigd5 (84% identical), guinea pig TIGD5 (83% identical), rat Tigd5 (81% identical), tropical clawed frog tigd5 (55% identical). Paralogues in human: JRKL (22% identical), TIGD1 (20% identical), JRK (20% identical), TIGD2 (20% identical), TIGD7 (19% identical), CENPB (19% identical), TIGD6 (19% identical), TIGD4 (18% identical), TIGD3 (16% identical), POGZ (13% identical), POGK (12% identical).
Diseases named in the same sentence as TIGD5 in open-access papers:
TIGD5 is named in the same sentence as 6 diseases in open-access papers, as found by Europe PMC text mining. Sharing a sentence is not in itself a finding about the gene and the disease. The quoted sentences say what the papers report.
breast carcinoma (1 paper, 2022). "To obtain evidence regarding the effects of serum factors on the expression of the CanCord34 genes, we examined the effects of serum starvation for 72 h on the levels of EEF1D, TIGD5, C8ORF73/MROH6, and BOP1 in the breast cancer SKBR-3, cervical cancer SiHa, and neuroblastoma IMR-32 cell lines." (PMID 36497066, 2022).
TIGD5 also shares sentences with these, for which no sentence is quoted: cancer (1 paper); cervical cancer (1); meningioma (1); neuroblastoma (1); tumour (1).